STAT3 (signal transducer and activator of transcription 3)
Diseases named in the same sentence as STAT3 in open-access papers (continued):
Sharing a sentence is not in itself a finding about the gene and the disease.
breast cancer (continued). "Both TGFβ stimulation and silencing of HnRNP E1 in breast cancer increase the translation of ILEI (oncogenic factor associated with EMT and tumorigenesis), which mediates signaling through STAT3, thereby inducing the formation of BCSCs (breast cancer stem cells) and promoting EMT." (PMID 36052258, 2022). "Despite evidence for the substantial role of IL-11 in inducing STAT3 activity in breast cancer, there is limited research examining how its blockade may be exploited therapeutically." (PMID 35053592, 2022). "M2 macrophages can also facilitate STAT3 signaling in breast cancer cells to promote tumor proliferation, and STAT3 activation in M2-polarized macrophages can activate STAT3 signaling in ovarian cancer cells to promote their growth via the production of IL-6 and IL-10." (PMID 36010693, 2022). "Furthermore, the Signal Transducer and Activator Of Transcription 3 (STAT3) upregulation has been reported to significantly increase the transcription of MEK5 in breast cancer (BC)." (PMID 35053510, 2022). "In addition to STAT3, IL-6 can be further activated through nuclear factor kappa B (NF-κB) signaling in breast cancer." (PMID 35371975, 2022). "Therefore, LIF can promote breast cancer migration and invasion, and the Stat3 signal is likely to participate in this process." (PMID 35280694, 2022). "Furthermore, EZH2 can interact with STAT3 and directly methylate STAT3, resulting in enhanced nuclear localization and chromatin of STAT3, thereby exacerbating breast cancer." (PMID 36313363, 2022). "The activation of the IL-6 and IL-11-dependent signaling cascade leads to the phosphorylation of STAT3 to transcriptionally activate genes and pathways that promote breast cancer proliferation, suppress apoptosis, allow for immune evasion leading to metastatic growth, and attain chemoresistance." (PMID 35053592, 2022). "In addressing this challenge, our work links ANXA1-FPR1/2 and STAT3, as functional partners of a paracrine/autocrine loop, between metastatic mammary cancer cells and microglial cells in supporting metastatic colonization of mammary cancer in the brain." (PMID 35382852, 2022). "To explore how LIF promotes cell migration and invasion in breast cancer, the downstream targets were detected and we found that selective inhibitors or siRNA of Stat3 leads to a decrease in the migration and invasion of breast cancer cells induced by rhLIF or CAAs." (PMID 35280694, 2022). "Targeting the IL-6 cytokine family/JAK/STAT-3 pathway may be a fruitful approach for early adjuvant breast cancer therapy and/or for preventing aggressive development of metastasis in secondary sites." (PMID 35163731, 2022). "Also, this ligand reduces the sensitivity of breast cancer cells to apoptosis and drug resistance through the Jak2/STAT3 signaling pathway." (PMID 35684481, 2022). "Indeed, over half of all primary human breast cancers and corresponding breast cancer cell lines show prominent accumulation of the activated form of the STAT3 transcription factor engaged by IL-6 signaling, suggesting widespread involvement of this pathway." (PMID 35565421, 2022). "p-STAT3 has been identified in 30–60% of primary breast cancer cases." (PMID 35314590, 2022). "Moreover, ARHGAP24 affects the STAT3 signaling pathway, which modulates the anti-cancer activity of sorafenib against breast cancer." (PMID 35812178, 2022). "In particular, the IL-6/STAT3 pathway was found to be preferentially active in CD44+CD24− breast cancer cells, which have stem-cell-like characteristics, compared with other tumor cell types, and the inhibition of JAK2 decreased their number and blocked the growth of xenografts." (PMID 36010693, 2022). "We and others have reported that Stat3 is activated in Ret-driven mammary tumors." (PMID 35044452, 2022). "MDSCs also endow stemness to breast cancer cells via IL-6/STAT3 and NO/Notch crosstalk signaling." (PMID 35805056, 2022).
breast cancer (continued). "To evaluate whether Stat3 mediates CAA-derived LIF to induce breast cancer cells migration and invasion, we examined the effects of Stattic, a specific Stat3 inhibitor, that inhibits Stat3 phosphorylation." (PMID 35280694, 2022). "The FDA has yet to approve IL-6/JAK/STAT3 pathway inhibitors for breast cancer." (PMID 35371975, 2022). "The present results suggested that STAT3 expression may play a different role in ER(−) and ER(+) breast cancer." (PMID 35314590, 2022). "This review covers the current biological understanding of the IL-6 signaling pathway and its impact on breast cancer metastasis, as well as, therapeutic interventions that target components of the IL-6 pathway including: IL-6, IL-6Rα, gp130 receptor, JAKs, and STAT3." (PMID 35371975, 2022). "An attempt to illustrate the role of ANXA1-FPRs axis in the crosstalk of metastatic mammary cancer cells and microglial cells, revealed that STAT3 as the downstream mediator of this interaction, working antagonistically to the ERK-STAT1 axis induced by 4T1 CM in BV-2 microglia." (PMID 35382852, 2022). "Therefore, multiple studies have investigated novel small-molecule compounds which negatively regulate STAT3 activation in breast cancer." (PMID 35371975, 2022). "In conclusion, the present study revealed, for the first time, the anti-proliferative, apoptotic, anti-migration and EMT inhibition activities of azilsartan against breast cancer cells through modulating NF-kB/IL-6/JAK2/STAT3/MMP9, TWIST/SNAIL/SLUG and apoptosis signaling pathways." (PMID 36431925, 2022). "LncRNA associated with breast cancer brain metastases (lnc-BM) is significantly upregulated in brain metastasis and influences TAM recruitment by inducing the production of CCL2 via JAK2/STAT3 pathway activation in cancer cells." (PMID 35202089, 2022). "Our previous studies had detected the miR-93-5p could inhibit breast cancer by regulating STAT3 signaling pathway." (PMID 35657638, 2022). "Moreover, IL-6 has also been reported to correlate with therapeutic resistance in breast cancer patients highlighting the IL-6/JAK/STAT3 pathway as an important prognostic marker in breast cancer progression, chemoresistance, and metastatic formation." (PMID 35371975, 2022). "WA is a herbal which promises the inhibition ofapoptosis in human breast cancer cells by mediating mitochondria as shown by Hahm (2011) and can inhibit the cell migration even after the activation of STAT3 by Interleukin-6(IL-6), which is a beneficial effect ofWA as shown by Lee (2010)." (PMID 37426503, 2022). "Furthermore, both Nrf2 and STAT3 are overexpressed in breast cancer, especially in basal-like breast cancer (BLBC)." (PMID 36557902, 2022). "The role of STAT3 in each breast cancer classified by biomarkers was recently clarified." (PMID 35314590, 2022). "Notably, STAT3 is persistently activated in various cancers, including breast cancer, and is often activated and required for the growth and survival of TNBC cells." (PMID 36009550, 2022). "Recent studies suggested that activated STAT3 (pSTAT3) might serve as a biomarker of outcome in breast cancer patients." (PMID 35327992, 2022). "STAT3, as one of the signal transducers and activators of transcription (STAT) family members, is highly activated in melanoma, breast cancer, lung cancer, pancreatic carcinoma and glioma, suggesting that STAT3 may be an effective target for tumour therapy." (PMID 36372977, 2022). "Pharmacologically suppressing STAT3/5 activation could induce an adaptive, compensatory mechanism to protect breast cancer cells from ROS by activating SLC7A11 transcription and the action of system xCT." (PMID 35884471, 2022). "Previous studies from our group demonstrated loss of PTEN in the breast cancer stroma results in an increase in ECM deposition and remodeling, suggesting STAT3 could be involved in modulating the ECM." (PMID 35803738, 2022).
breast cancer (continued). "Milk-fat globule-epidermal growth factor-VIII (MFG-E8) from TAMs conferred CSC-amplified cisplatin (CDDP) resistance in breast cancer by manipulating the activation of the signal transduction and transcription activator 3 (STAT3) and sonic hedgehog signaling pathways." (PMID 36359776, 2022). "Our data suggest that miR-23c may interfere with IL-6R/STAT3 signaling in breast cancer cell lines and that the upregulation of miR-23c in these cells reduces cell proliferation and migration by inhibiting IL-6R/STAT3 signaling." (PMID 35406622, 2022). "In addition, STAT3 has been found to up-regulate aerobic glycolysis and promote the proliferation of glioblastoma, bladder cancer, and breast cancer." (PMID 36188586, 2022). "Among them, IL-6 is critical for STAT3 activation in human breast cancer." (PMID 36009550, 2022). "p-STAT3 expression was examined in 135 cases of breast cancer by immunohistochemistry." (PMID 35314590, 2022). "It has been reported that LIF oncogenic activity is mediated by STAT3 phosphorylation and translocation to the nuclei, and our group has reported that activation of this transcription factor in mammary tumor cells is dependent on paracrine/autocrine LIF secretion." (PMID 35163731, 2022). "Thus, our data demonstrates that TAM derived IL-6 mediates STAT-3 dependent enrichment of CSCs in breast cancer." (PMID 35300689, 2022). "Elevated expression or gene amplification of STAT3 and its upstream activators may be used as a prognostic indicator in breast cancer." (PMID 35053592, 2022). "Furthermore, evidence has shown that GPX8 maintains an aggressive breast cancer phenotype by regulating the interleukin 6 (IL-6)/JAK/STAT3 signaling pathway, which is hyperactivated in many different malignancies and is generally linked to a poor prognosis." (PMID 35456975, 2022). "We considered it a necessity to explore whether LIF can regulate the migration and invasion of breast cancer cells through activation of the Stat3 signaling pathway." (PMID 35280694, 2022). "miR-142-3p, which suppresses expression of the oncogene HMGA1 and targets the AKT/ERK/STAT3 pathway, is supposed to be a new miRNA for breast cancer therapy that restores this suppressive miRNA in tumor breast cells using a targeted nanoparticle delivery system." (PMID 36555323, 2022). "Notably, Stat3 is constitutively active in invasive breast cancers and, when expressed in tumour epithelial cells, is crucially important in promoting an immunosuppressive microenvironment both during tumour initiation and progression." (PMID 35420674, 2022). "Studies show that STAT3 activation is associated with the M2 isozyme of pyruvate kinase (PKM2)/HIF‐1α positive feedback loop and promotes proliferation of many types of cancer cells, such as human HCC cells, breast cancer cells, and colorectal cancer cells." (PMID 35356799, 2022). "In the future, the pharmacological inhibition of STAT3 expression may serve as an effective therapeutic strategy for ER(−) breast cancer, particularly TNBC." (PMID 35314590, 2022). "A large number of studies have shown that IL-6/JAK2/STAT3 signaling pathway is abnormally highly activated in a variety of cancers, such as gastric cancer (GC), breast cancer (BC), liver cancer, colorectal cancer (CRC), colon cancer, ovarian cancer (OC), lung cancer, pancreatic cancer (PC)." (PMID 36591515, 2022). "In addition, chronic stress promotes breast cancer metastasis by activating the STAT3 signal pathway through Mir-337-3p." (PMID 34988010, 2021). "However, the effects of STAT3 cascade on immune cells in breast cancer tumor immune microenvironment is yet to be elucidated." (PMID 33957948, 2021). "Besides, CDK5RAP3 in breast cancer cells is reported to positively regulates the transcriptional activity of signal transducer and activator of transcription 3 (STAT3), an oncogenic transcription factor, to trigger its tumorigenic phenotypes." (PMID 34722315, 2021).
breast cancer (continued). "Notably, MDSCs are another class of immune cells which are regulated by cancer cell-derived exosomal miRNAs; miR-17-5p (breast cancer) and miR-20a (in several cancers) promote the STAT3-mediated suppressive function of MDSCs." (PMID 34122412, 2021). "Furthermore, STAT3-mediated IDO1 expression was found to be upregulated in breast cancer cell-induced MDSCs, which suppressed effector T cells and hyperactivated the infiltration of the Foxp3+ Tregs in TME." (PMID 33957948, 2021). "Hence, LIFR : STAT3 signaling appears to confer a dormancy phenotype in breast cancer cells disseminated to bone." (PMID 33987095, 2021). "Moreover, primaquine and chloroquine induce the apoptosis of breast cancer cells through c-Myc/Bcl-2 downregulation, induce early endosome damage and reduce nEGFR levels, and induce apoptosis in breast cancer through nEGFR/Stat3-dependent c-Myc downregulation." (PMID 34884765, 2021). "In breast cancer, the STAT3 inhibitors presented a positive feedback in tumor intervention." (PMID 33957948, 2021). "Furthermore, the crosstalk between TAMs and breast cancer cells showed an ability to induce CSCs phenotype formation with upregulated Sox-2 expression via activation of STAT3 cascade." (PMID 33957948, 2021). "However, in vitro studies have reported that an increased ATX was related to the activation of STAT3 in both breast cancer and pancreatic neuroendocrine neoplasms." (PMID 34722305, 2021). "We deduce that STAT3 might regulates EZH2 expression which constitutes the 'vicious cycle' with STAT3 methylation by EZH2 in breast cancer." (PMID 34335938, 2021). "Knock down of STAT3 in TME of breast tumor results in the downregulation of the surface expression of on tumor cell via the DCs activation, and HER-2/neu is a proto-oncogene linked to breast cancer progression and metastasis." (PMID 33957948, 2021). "STAT3 is constitutively activated in many cancers, including breast cancer." (PMID 33605027, 2021). "Tyrosine phosphorylated STAT3 was also significantly reduced in secondary tumors in vivo that originated in wildtype recipient females from the transplantation of MMTV-Flp FSF-KrasG12D Rosa26CAG-FSF-CreERT2 Jak1fl/fl mammary tumor cells and treatment with Tam." (PMID 34675248, 2021). "We then analyzed the function of circNOLC1/STAT3 axis in the regulation of breast cancer functions." (PMID 34789263, 2021). "LUT may augment the impact of anticancer drugs to control breast cancer by reducing drug resistance (tamoxifen by inhibiting cyclin E2 expression), promoting apoptosis (by blocking STAT3), and inhibiting breast cancer cell growth." (PMID 34452179, 2021). "Altogether, this teaches us that STAT3 phosphorylation downstream to IL-6 signalling could suppress breast cancer development and progression." (PMID 34047814, 2021). "Therefore, STAT3 signaling is a most potential therapeutic target for breast cancer systematic immunotherapy." (PMID 33957948, 2021). "Inhibitors of STAT3 have been reported to inhibit cell proliferation and promote the apoptosis of lung cancer, gastric cancer, colorectal cancer, leukemia, melanoma, renal cancer and breast cancer, to name a few." (PMID 33957948, 2021). "Next, we aimed to further validate the role of STAT3 in selectively packaging miR-378a-3p and miR-378d into exosomes and found that miR-378 expression was positively correlated with STAT3 expression in breast cancer based on the TCGA database (n = 470) (p < 0.001)." (PMID 33823894, 2021). "Besides, the mRNA and protein expression of STAT3 were significantly repressed by miR-106a-5p mimic in the cells, suggesting that miR-106a-5p is able to target STAT3 in the breast cancer cells." (PMID 33686957, 2021). "Tim-3 overexpression in breast cancer cells activated the STAT3 signal pathway, and then maybe converged in both tumor promotion and immunosuppression, such as the crosstalk between tumor cells and immune cells." (PMID 34504800, 2021).
breast cancer (continued). "For epithelial-mesenchymal transformation (EMT) in breast cancer, STAT3 (a critical signaling node in EMT) may be part of a positive feedback loop with PIM2 kinase that contributes to the progression of breast cancer." (PMID 33854618, 2021). "JAK2 knockdown (KD) in human acute myelogenous leukemia (AML) cell line, STAT1 KD in human T cell acute lymphocytic leukemia cells, Stat3 KD in mouse mammary tumor, and STAT3 KD in human urothelial cancer cells resulted in zero to two OCRG upregulation and one to five OCRG downregulations." (PMID 34368262, 2021). "The inhibition of STAT3 in migratory cDCs might be a novel immunotherapy strategy for management of metastatic and advanced breast cancer." (PMID 33957948, 2021). "Furthermore, the high concentration of TNF-α and IL-6 mediated JAK2/STAT3 pathway activation to induce phenotypic change into breast cancer cells with SC properties." (PMID 34122412, 2021). "Therefore, constitutive activation of STAT3 regulates MDSCs and anti-cancer T lymphocytes population in breast cancer TME." (PMID 33957948, 2021). "They found that exosomes isolated from macrophages after coculture with apoptotic breast cancer cells demonstrated the ability to induce proliferation, invasiveness, and metastasis of breast cancer in vitro and in vivo by activating STAT3 and its target genes CyclinD1, MMP2, and MMP9." (PMID 34207035, 2021). "It was shown that knocking down EZH2 could significantly decreased nuclear retention of STAT3 in breast cancer cells." (PMID 34335938, 2021). "Collectively, these findings suggest that targeting STAT3 may lead to a potent anti-tumor T cells immune response in breast cancer with pleiotropic functions." (PMID 33957948, 2021). "In addition, STAT3-inhibitor S3I-201, simultaneously suppressed the STAT3 phosphorylation and macrophages transformation in breast cancer TME as compared to control." (PMID 33957948, 2021). "Thus, we concluded that circNOLC1 contributes to CSCs properties and progression of breast cancer by targeting miR-365a-3p /STAT3 axis and propofol inhibited circNOLC1 by repressing STAT3 in a feedback mechanism." (PMID 34789263, 2021). "CXCL3 promoted breast cancer cell proliferation through the JAK2/STAT3 signaling pathway." (PMID 34870709, 2021). "In addition, the TIMER database showed that S1PR1 and STAT3 had positive connections in breast cancer, and STAT3 and VEGFA were positively connected." (PMID 34059068, 2021). "Against this backdrop, modulating the intercellular STAT3 cascade of macrophages may provide an opportunity to improve therapeutic efficacy of the breast cancer immunotherapy." (PMID 33957948, 2021). "Similarly, nifuroxazide was reported to produce breast cancer cell apoptosis and prevent pulmonary metastasis in 4T1 cells grown in mice via inhibition of STAT3." (PMID 34833950, 2021). "Also, the double bond of the α, β-unsaturated carbonyl moiety of 15-keto prostaglandin E2 was found to be crucial for the inhibition of both STAT3 activation in breast cancer cells and breast tumor growth in a xenograft mouse model." (PMID 34829746, 2021). "However, it has been shown that STAT3 overexpression has been shown to promote human breast cancer and thyroid carcinoma cell proliferation." (PMID 34239543, 2021). "Therefore, the blockade of STAT3 by inhibitors is considered to be a promising direction for tumorigenesis and metastasis inhibition in breast cancer, and, notably, curcumin has been reported as a potent inhibitor." (PMID 34298639, 2021). "Finally, this proof-of-principle study provides evidence that the JAK1 tyrosine kinase plays a central role in the constitutive activation of STAT3 in KRAS-transformed mammary cancer cells." (PMID 34675248, 2021).